DRD4 (dopamine receptor D4)
Diseases named in the same sentence as DRD4 in open-access papers (continued):
Sharing a sentence is not in itself a finding about the gene and the disease.
attention deficit-hyperactivity disorder (28 papers, 2005 to 2026). A disorder characterized by a marked pattern of inattention and/or hyperactivity-impulsivity that is inconsistent with developmental level and clearly interferes with functioning in at least two settings (e.g. at home and at school). "Several meta-analyses identified the DRD4-7R allele as a risk allele for attention deficit hyperactivity disorder (ADHD), a disorder characterized by high impulsivity." (PMID 40943571, 2025). "The DRD4 48 bp VNTR polymorphism has been previously linked to Attention-deficit/hyperactivity disorder (ADHD) phenotypes." (PMID 26307064, 2015). "Another example is the 7-repeat variable number tandem repeat (VNTR) in the DRD4 gene with individuals showing a greater risk for attention deficit hyperactivity disorder (ADHD) and for SUD." (PMID 25077169, 2014). "So far evidence suggests that there is an association between the DRD4 7 repeat allele and attention deficit hyperactivity disorder (ADHD) also, although the effect size is small." (PMID 15985158, 2005). "DRD4 polymorphisms have been associated with individual differences in impulse control-related neuropsychiatric disorders, with the most consistent associations found between the gene encoding D4.7R and attention-deficit hyperactivity disorder (ADHD) and substance use disorders (SUDs)." (PMID 36267569, 2022). "DRD4 polymorphisms have been associated with individual differences linked to impulse control-related neuropsychiatric disorders, with the most consistent associations established between the gene encoding D4.7R and attention-deficit hyperactivity disorder (ADHD) and substance use disorders." (PMID 36267569, 2022). "Besides sensation seeking in toddlers when combined with poor parenting, DRD4 gene polymorphisms have been associated with several other phenotypes, including an increased risk of attention deficit hyperactivity disorder (ADHD), impulsivity, and lower levels of response inhibition." (PMID 34072960, 2021). "The dopamine receptor D4 (DRD4) is one of the most studied candidate genes for Attention-Deficit/Hyperactivity Disorder (ADHD)." (PMID 24391992, 2013). "Also, traits associated with types of Attention Deficit Hyperactivity Disorder (ADHD) have been linked with imbalances in the dopamine and norepinephrine systems, as well as a specific allele in the dopamine receptor D4 gene." (PMID 26284018, 2015). "Besides reported associations between the DRD4 exon III polymorphism and various phenotypes related to decision making behavior like impulsivity, novelty seeking, gambling behavior and attention-deficit hyperactivity disorder (ADHD) the functionality of this polymorphism has been demonstrated." (PMID 23759976, 2013). "We examined bidirectional relations between attention-deficit/hyperactivity disorder (ADHD) symptoms and family and school climate, and the possible role of DRD4 and/or 5-HTTLPR genotypes herein." (PMID 31628528, 2020). "Influence of attention deficit/hyperactivity disorder (ADHD) and DRD4 gene on the lateral prefrontal gyrification and thickness in ADHD." (PMID 31105599, 2019).
Anxiety (15 papers, 2006 to 2025). Intense feelings of nervousness, tension, or panic often arise in response to interpersonal stresses. "Direct effects of the DRD4 polymorphisms on children’s personality only appeared for CCQ anxiety, specifically at age twelve." (PMID 35496066, 2022). "We observed an effect of SLC6A4 5-HTTLPR + rs25531 locus on depressive and personal anxiety symptoms and an effect of DRD4 48 bp VNTR-polymorphism on situational anxiety." (PMID 34199792, 2021). "Of note, this is the first study to suggest that the presence of the 4,5 genotype of DRD4 exon III polymorphism is associated with an increased risk of anxiety symptoms among HD patients." (PMID 33784353, 2021). "Binary logistic regression analyses showed that the heterozygous 4,5 VNTR genotype of DRD4 was associated with a higher risk of anxiety symptoms after adjusting for other covariates (odds ratio = 4.25, p = 0.028)." (PMID 33784353, 2021). "Genotype and allele frequencies of the DRD4 VNTR polymorphism were significantly different between anxiety cases versus normal-borderline subjects." (PMID 33784353, 2021). "Collectively, the current findings provide genetic clues to psychopathology in HD patients and suggest that the DRD4 exon III VNTR polymorphism is involved in the etiology of anxiety in this patient population." (PMID 33784353, 2021). "The current study revealed that DRD4 VNTR 4/5 genotype was associated with anxiety status in Jordanian HD patients and, as a consequence, has significantly advanced the state of research in this area." (PMID 33784353, 2021). "Significant differences were observed in the distribution of 5-HTTLPR genotypes, SLC6A4 tri-allelic-phased genotype, and DRD4-Exon III VNTR genotypes/alleles between patients with anxiety symptoms versus those with normal/borderline conditions (p<0.05)." (PMID 33784353, 2021). "A previous analysis of 196 Japanese subjects showed a significant association between short alleles (2–4 repeats) within the DRD4 gene and personality trait of neuroticism, such as anxiety." (PMID 33784353, 2021). "The DRD4 gene affects the activity of dopamine and is involved in many neurological processes, it shows polymorphism, and is one of the various genes studied in connection with psychiatric disorders, anxiety, and stress." (PMID 33784353, 2021). "In conclusion, the heterozygous genotype (4/5) in the DRD4 gene could be a genetic risk factor linked with anxiety in HD." (PMID 33784353, 2021). "One possible explanation is that genetically linked risk for ADHD (DRD4-7R carriers and males) is tied to more generalized and stable brain-function characteristics, while more experience-linked conditions (mood and anxiety) involve more state and/or circumstance specific abnormal brain functioning." (PMID 25999865, 2015). "Genotype for 5-HTTLPR, STin and AVPR1a, and haplotype for HTR2A, DRD4 and OXTR were significantly associated with the duration of behaviours including fear and anxiety." (PMID 37531334, 2023). "Accordingly, the role of DRD4 in anxiety-related behaviours remains ambiguous and requires further research." (PMID 36854793, 2023). "The study revealed significant variations in the distribution of various genotypes and alleles of DRD4 VNTR and 5-HTTLPR polymorphisms according to the anxiety scores of patients." (PMID 33784353, 2021). "RPA was broadly expressed in DRD4 7R carriers and males, but specifically expressed in mood and anxiety groups." (PMID 25999865, 2015). "Here we show that variants of two genes that regulate dopamine and serotonin neurotransmission and have been previously linked to emotional behavior, anxiety and addiction (5-HTTLPR and DRD4) are significant determinants of risk taking in investment decisions." (PMID 19209222, 2009). "DRD4 48 bp VNTR-polymorphism was significantly associated with levels of personal anxiety in patients but not with the risk of attempted suicide." (PMID 34199792, 2021).
Anxiety (continued). "Carriers of the 4,5 genotype of the DRD4 VNTR polymorphism had 4.25 odds (p = 0.028) of developing anxiety symptoms compared to the carriers of the wild type 2,4 genotype, while DRD4 VNTR alleles were not linked to anxiety." (PMID 33784353, 2021). "The effect of DRD4 and SLC6A4 polymorphisms on anxiety adjusting for other covariates." (PMID 33784353, 2021). "Furthermore, DRD4 haplotypes may contribute to psychopathological features, including anxiety in subjects with eating disorders." (PMID 33784353, 2021). "The most obvious difference across ADHD RFs was that DRD4-7R and males exhibited RPA in multiple brain regions, frequencies, and conditions, whereas mood and anxiety showed very specific effects." (PMID 25999865, 2015). "DRD4-7R carriers showed a link between RPA and fewer inattentive symptoms, and two of eighteen significant effects for anxiety showed a link between RPA and reduced hyperactivity." (PMID 25999865, 2015). "The investigation focused on the behavioural effects of the recently developed DRD4 agonist, APH199, to evaluate its impact on anxiety, anhedonia, behavioural despair, establishment and retrieval of alcohol reinforcement, and amphetamine (AMPH)-induced symptoms." (PMID 36854793, 2023). "Effects were broadly expressed for DRD4 7R carriers and males, but specific for mood, anxiety, and non-right handedness." (PMID 25999865, 2015). "Similarly, inhibition of DRD4 has shown no influence on the anxiety levels of mice in the elevated plus maze (EPM) and open field (OF) tests." (PMID 36854793, 2023).
Obesity (12 papers, 2012 to 2025). Accumulation of substantial excess body fat. "In relation to DRD4-VNTR, the patients carrying one or two DRD4-L variants in DRD4-VNTR had a tendency for a higher risk of obesity BMI than patients carrying two DRD4-S variants In DRD4-VNTR (X2: 3.54, df: 1, p = 0.060, OR: 1.77 [1.01–3.09])." (PMID 37631349, 2023). "Humans who are homo- or heterozygous for DRD4 7R + alleles have shown higher peak body mass in cohorts at risk for obesity, greater food cravings, as well as smoking, alcohol, and drug cravings." (PMID 24283216, 2013). "Although the work was limited only to obese patients with a small range of BMI, without a direct correlation between the Karolinska Scales of Personality and DRD4 long allele, the results of this study revealed an association between this polymorphism and obesity susceptibility." (PMID 32751662, 2020). "One of the possible candidates that may contribute to the dysregulation of feeding patterns in ED and risk of weight gain, leading to obesity, is the polymorphism of DRD4 gene." (PMID 32751662, 2020). "However, as previously discussed, the sex-specific effects we observed are consistent with environmental, as well as biological, correlates of sex modulating effects of DRD4 expression, supporting the overall model that DRD4 expression modulates environmental effects on obesity risk." (PMID 34916545, 2021). "We hypothesized, that the presence of DRD2 rs1800497 T and/or DRD4 7R + alleles are more frequent among overweight/obese vs. lean subjects and are associated with weaker reduction of overweight after a 1 year childhood obesity intervention." (PMID 24283216, 2013). "These considerations on DRD4 distribution and the role in drug dependence, previously debated, provide evidence on the potential implication of DRD4 signaling in ED and obesity." (PMID 32751662, 2020). "Dopaminergic gene polymorphisms such as DRD4, COMTVal158Met, and DAT1 have been linked to affective disorders in obesity." (PMID 30991630, 2019). "Therefore, the finding that individuals carrying genetic variants in DRD2, DRD4, and DAT1 and low MLGP score, associated with a hypofunctional DA system, are related to alterations in cardiometabolic parameters linked to obesity reinforce our results and hypothesis." (PMID 37631349, 2023). "Recent data that we published showed a decrease in DRD4 and DRD1 expression with the onset of insulin resistance, while DRD2 expression remained unchanged with the progression of metabolic dysregulation in obesity." (PMID 36768789, 2023). "Although the subject did not present ADHD or other psychiatric disorder, many symptoms possibly related to the absence of DRD4 protein were observed, such as somatic ailments, obesity and disturbances of the autonomic nervous system." (PMID 24391992, 2013).
alcohol dependence (11 papers, 2012 to 2023). Physical and psychological dependence on alcohol. "In Western studies, the 48 bp VNTR polymorphism in the DRD4 gene has been associated with a number of addictive disorders, including substance abuse, alcohol dependence, and smoking." (PMID 30572854, 2018). "A significant allelic and genotypic associations of −48 A > G SNP of DRD1 and −120 Ins/Del polymorphism of DRD4 were observed with alcohol dependence." (PMID 24135011, 2013). "Statistically significant associations of polymorphisms in DRD1 and DRD4 with alcoholism were found." (PMID 24135011, 2013). "In fact, studies with rats show that those with higher levels of dopamine transporters show more impulsivity towards small rewards or in humans, for example, the 7R+ allele of DRD4 has been linked to various risk behaviors such as alcoholism, impulsivity, sexual promiscuity and even infidelities." (PMID 36361187, 2022). "The results of this study suggest that inherited short variants of DRD4 alleles (3R) may play a role in the pathogenesis of alcohol dependence and carriers of the 4R may have a protective effect for alcoholism risk behaviors." (PMID 24878765, 2014). "A meta-analysis of the relationship between D2 dopamine receptor gene and alcoholism reported that alcoholics had a higher prevalence of the A1 allele than controls, whereas another meta-analysis of dopaminergic receptors indicated a weak association between DRD4, DAT gene and smoking initiation." (PMID 37906564, 2023). "We tested genetic association of three polymorphisms in the dopaminergic pathway genes namely rs4532 in DRD1, rs6280 in DRD3 and a 120 bp duplication in 1.2 kb upstream region of DRD4 with alcohol dependence among male subjects from the North India." (PMID 24135011, 2013). "Association of DRD4 with alcohol dependence has not been largely investigated." (PMID 24135011, 2013).
substance abuse (10 papers, 2010 to 2024). The use of a drug for a reason other than which it was intended or in a manner or in quantities other than directed. "Genotype and allele distribution of COMT and DRD4 genes polymorphisms in substance abuser and control." (PMID 33544778, 2021). "Association of genetic polymorphisms of COMT and DRD4 genes with the age of onset of substance abuse." (PMID 33544778, 2021). "The Dopamine D4 receptor (DRD4) gene VNTR polymorphisms have also been association with substance abuse in several studies." (PMID 33544778, 2021). "The highly polymorphic nature of the DRD4 gene seems to be a potential genetic susceptibility factor to the development of substance abuse and is correlated with addiction and addiction associated-phenotypes." (PMID 32751662, 2020). "The DRD4 l-allele has been associated with substance abuse and the rewarding effects of social context (e.g., social bonding), thus suggesting a role for this variant in the processing of rewarding stimuli." (PMID 26974654, 2016). "The present study hypothesized that the carrier of the derived allele of both COMT Val158Met and DRD4 120 tandem duplication polymorphisms in the dopaminergic system are associated with the risk of substance abuse." (PMID 33544778, 2021). "Therefore, the present study is carried out to investigate the association of genetic polymorphism of COMT and DRD4 as a biomarker for increased risk of substance abuse in Bangladesh." (PMID 33544778, 2021). "In conclusion, the present study has demonstrated a significant association of COMT heterozygous variant polymorphism (Val/Met) as well as both homozygous and heterozygous variants of DRD4 120 bp tandem duplication with risk of substance abuse among the Bangladeshi population." (PMID 33544778, 2021). "Whereas, the homozygous derived variant (240 bp/240 bp) of DRD4 gene was found to have a later age of onset (20.5±0.8) for substance abuse compared to heterozygous (120 bp/240 bp) (19.1±0.8) and wild type homozygous variant (120 bp/120 bp) (16.0±0.5), which was statistically significant (p<0.05)." (PMID 33544778, 2021). "Further, all the addicted subjects were categorized into three groups- methamphetamine, heroin, and cannabis abusers to analyze whether these COMT and DRD4 polymorphisms can have any influence on the age of onset of individual substance abusers." (PMID 33544778, 2021). "Besides DRD2 gene products, dopamine receptor D4 (DRD4) gene polymorphism is also independently linked to both substance abuse, including cannabis use and internalizing disorders." (PMID 32455076, 2020). "Consequently, the deficiency in DRD4 signaling, particularly evident in the 7R variant of the gene, could increase the susceptibility to the development of substance abuse or ED and related comorbidities." (PMID 32751662, 2020). "In summary, while this study has some restrictions, it is the first research in which the relationship between COMT Val158Met and DRD4 120bp VNTR variant and substance abuse in the Bangladeshi population were analyzed." (PMID 33544778, 2021). "In the next paragraphs we will analyze genetic studies linking the DRD4 gene to substance abuse and preclinical studies that investigated the role of this receptor in drug dependence." (PMID 32751662, 2020). "None of the DRD4 promoter SNPs showed significant association with substance abuse using either the 3 or 2 genotype categories." (PMID 20205808, 2010). "Therefore, similar to HTR2B, decreased DRD4 might promote the common covariation of substance abuse with BP and SCHIZ." (PMID 37031222, 2023). "Furthermore, many other SNPs across the DRD4 5’ flanking region (promoter) may also effect the functions of DRD4, and even the onset ages of substance abuse." (PMID 33544778, 2021). "There are five dopamine receptor genes, DRD1, DRD2, DRD3, DRD4, and DRD5, which are mainly related to different risky behaviors like substance abuse and addiction." (PMID 38254998, 2024).
substance abuse (continued). "The application of highly selective DRD4 agonists could significantly improve the cognitive ability of ADHD model rats; moreover, it did not increase the risk of substance abuse compared with psychostimulant therapy." (PMID 36133787, 2022).
alcohol use disorder (9 papers, 2012 to 2023). "Carriers of the DRD4 7R allele showed greater susceptibility to alcohol use disorder and opioid use disorder." (PMID 34828440, 2021). "Szczepankiewicz and colleagues investigated the possible relationship between polymorphisms in the four dopamine receptor genes (−48 A/G in DRD1, −141 C ins/del in DRD2, 9 Ser/Gly in DRD3, and −521 C/T in DRD4) and the comorbidity of alcohol abuse in bipolar patients." (PMID 35893041, 2022). "Although, we assume that the effects of DRD4 modulators might be determined by the specific behavioural model, reinforcing drug or animal species; our experiments, in line with previous research, have not indicated a significant impact of the agonists on an animal model of alcohol abuse." (PMID 36854793, 2023).